MAP2 (microtubule associated protein 2)
Diseases named in the same sentence as MAP2 in open-access papers (continued):
Sharing a sentence is not in itself a finding about the gene and the disease.
Cognitive impairment (21 papers, 2013 to 2025). Abnormal cognition is characterized by deficits in thinking, reasoning, or remembering. "The increased expression of BDNF, VEGF, and MAP2 in the DAI-T group supports the potential use of rTMS in treating cognitive impairments associated with DAI." (PMID 39051213, 2024). "MAP2 loss and dendritic pruning are morphological defects clearly associated with cognitive impairment in PLWH and in EcoHIV-infected mice." (PMID 38793575, 2024). "Previously, NSTyr had mitigated the cognitive deficits and restored hippocampal levels of the microtubule-associated protein 2 (MAP-2) and the synaptophysin protein in rats subjected to CCH." (PMID 29904335, 2018). "The cognitive impairments appear to be a result of progressive neuronal loss as determined by decreased immunoreactivity to neuronal markers such as NeuN and MAP2 and the loss of myelinated axons in CA1, probably coming from the CA3 and entorhinal cortex." (PMID 26888634, 2016). "Alterations in MAP2 expression were also reported in animal models of mental disorders, e.g., animals showing cognitive impairment or abnormal behavior relevant to schizophrenic symptoms." (PMID 39595042, 2024). "In the (human cytomegalovirus) HCMV‐UL122‐Tg mouse model, it was found to have more significant cognitive impairment than the 6‐month‐old mice, and the expression of MAP2 in the hippocampus was also reduced." (PMID 39691419, 2024). "In the UL122 mice, the increased expression of CPEB3 induced by long-term stably expressed IE2 impaired synaptic plasticity through downregulating the expression of PRPs (PSD95 and MAP2), finally resulting in cognitive impairment." (PMID 34790111, 2021). "It is noteworthy that decreased MAP2 expression at synapses precedes the appearance of AD plaques, suggesting that MAP2 alterations may serve as early markers of synaptic pathology and cognitive impairment." (PMID 40223095, 2025). "Similarly, our Western blot data suggested that elevated circulating TMAO could downregulate synaptic plasticity-associated proteins, including synaptophysin, MAP-2, and PSD-95, which led to cognitive deficits in the rats." (PMID 36429082, 2022). "Short term treatment with CBD in mice model of BCCAO has been shown to prevent motor and cognitive impairment through a complex mechanism related with stimulation of synthesis in the hippocampus of the levels of BDNF and MAP-2 proteins and stimulation of neurogenesis." (PMID 32726998, 2020). "In conclusion, we have examined the expression patterns of MAP2 and tau in the hippocampal formation subfields of MTLE patients with and without psychiatric comorbidities and have correlated them with features indicative of cognitive impairment." (PMID 24069608, 2013).
Cerebral ischemia (19 papers, 2013 to 2025). Restriction of arterial blood supply to the brain associated with insufficient oxygenation to support the metabolic requirements of the tissue. "The results showed that inducing cerebral ischemia after a week of excessive microplastic ingestion significantly reduced microtubule-associated protein 2 (MAP2) and myelin basic protein (MBP), as confirmed by immunohistochemistry." (PMID 39996714, 2025). "Furthermore, spatial memory performances were positively correlated with an increase of both newborn cell survival in bilateral dentate gyrus and restored microtubule-associated protein 2 (MAP2) density after cerebral ischemia." (PMID 27445801, 2016). "Among cytoskeletal elements, MFAP5 exhibited a local arrangement and morphological characteristics due to focal cerebral ischemia comparable to NF-L and MAP2." (PMID 40548074, 2025). "Since, neuronal loss volume is the most straightforward indicator for assessing the severity of cerebral ischemia, we performed MAP2 immunostaining." (PMID 39519316, 2024). "This study demonstrated that MAP2 protein expression and NeuN-positive cells in brain tissue on the ischemic side were significantly increased after exosome treatment in cerebral ischemia." (PMID 36297399, 2022). "The CORM-3-treated tMCAO group had significantly higher levels of NeuN and MAP2 than did the saline-treated tMCAO group on day 3 after brain ischemia." (PMID 29929562, 2018). "In contrast, a transient decrease in the immunoreactivity for MAP2 per unit volume was observed only at 1 day after cerebral ischemia (P = 0.06)." (PMID 28195185, 2017). "The combination of the BYHWD and physical exercise treatment alleviated the decreases in the SYN, GAP-43 and MAP-2 proteins after the cerebral ischemia." (PMID 28351388, 2017). "Wild-type and TFF3-/- mice exhibited similar changes in the pattern and distribution of MAP2 in cerebral ischemia/reperfusion injury." (PMID 24204940, 2013). "In cerebral ischemia/reperfusion injury, neuronal MAP2 filaments and speckles were disassembled within 24 hrs, and MAP2 was dispersed uniformly throughout the cytoplasm." (PMID 24204940, 2013). "This regional difference in hippocampal MAP-2 expression following cerebral ischemia remains unclear." (PMID 40869376, 2025). "Immunosignals of tricellulin, MFAP5 and α-catenin were quantified along with signals from the cytoskeletal elements MAP2 and NF-L at the ischemic border zone of the neocortex and subcortex in brain tissues from mice subjected to 24 h of focal cerebral ischemia." (PMID 37569268, 2023). "The association between dendritic pathology and changes in the expression of MAP-2 has been postulated in brain and spinal cord studies on rabies virus-infected mice and in other pathologies, such as cerebral ischemia, Rett syndrome, Down syndrome, and epilepsy." (PMID 37631975, 2023). "Post hoc analysis showed that BHD treatment elevated the cell number of Ki67+, Ki67/MAP-2+ and Ki67/GFAP+ in the peri-infarct cortex following cerebral ischemia." (PMID 40973940, 2025). "Double immunofluorescence staining for NeuN/Caspase1, NeuN/GSDMD, NeuN/IL-1β, MAP2/ASC, MAP2/GSDMD and NLRP1/GSDMD further confirmed that iTBS post-treatment is capable of inhibiting cerebral ischemia-induced pyroptosis of neuron in peri-infarcted area rather than at the border of infarcted core." (PMID 35690810, 2022). "We demonstrated that endothelial proliferation and subsequent angiogenesis were activated at the border area within the MAP2-negative ischemic core but not in the ischemic penumbra from 7 days after cerebral ischemia." (PMID 28195185, 2017). "Although MAP2 and NF-L have particularly proven as ischemia-sensitive elements of the neuronal cytoskeleton in various studies, a simultaneous region- and time-dependent characterization among different models of focal cerebral ischemia is not yet available." (PMID 33931805, 2021).
Cerebral ischemia (continued). "We speculated that the border area within the MAP2-negative ischemic core might be a novel therapeutic target area against cerebral ischemia." (PMID 28195185, 2017).
ischemic stroke (17 papers, 2010 to 2025). A stroke disorder caused by obstruction of blood flow to the brain, due to thrombotic (local blood clot formation) or embolic (due to a blood clot or other material traveling from another site) event. "The microtubule-associated protein 2 (MAP-2) is a postsynaptic protein and a sensitive marker of ischemic stroke, the loss of which often indicates neuronal dysfunction." (PMID 36133805, 2022). "Numerous studies have reported that transplanted MSCs in animals with ischemic stroke expressed the neural cell lineage markers, such as the neuronal-specific protein NeuN, microtubule-associated protein 2 (MAP-2), and the astrocytic marker GFAP." (PMID 21939558, 2011). "Long‐term neuronal death following ischemic stroke resulted in brain atrophy, as shown by MAP2 immunostaining 28 days after tFCI." (PMID 39915908, 2025). "Quantitative immunohistochemical analysis revealed the beneficial effect of BHD treatment on the neurogenesis in the peri-infarct area following ischemic stroke, as evidenced by the elevated cells number of Ki67+, Ki67/MAP-2+ and Ki67/GFAP+." (PMID 40973940, 2025). "Inhibiting cofilin rod aggregation by overexpression of LIMK rescued the MAP2 and attenuated the apoptosis, suggesting cofilin in direct inhibition as a treatment option for the ischemic stroke." (PMID 37190062, 2023). "Similarly, brain tissues from patients with ischemic stroke exhibited evident colocalization of Kla and MAP2 staining, highlighting the potential involvement of Kla in the neuronal response to ischemic injury." (PMID 40271828, 2025). "To increase the robustness of the behavioral and histological assessment, meanwhile, we checked the neurological severity scores (NSS) along ischemic stroke over time, the the expression of neuronal marker Map2 and NeuN and the fluorescent Nissl morphology in the serial post-ischemic brain slices." (PMID 38491167, 2024). "One study on ischemic stroke in rodents, demonstrated an upregulation of MAP2 in the penumbral—injured but not necrotic—region, which was attributed to ongoing neuronal repair." (PMID 37443041, 2023).
epilepsy (15 papers, 2013 to 2025). A brain disorder characterized by episodes of abnormally increased neuronal discharge resulting in transient episodes of sensory or motor neurological dysfunction, or psychic dysfunction. "Several studies have shown that pilocarpine-induced epilepsy causes microtubule-associated protein 2 (MAP2) disruption in the hippocampus." (PMID 38671837, 2024). "Moreover, altered expression of Map2 (dendritic microtubule-associated protein) and Jun (c-Jun) was reported in epilepsy." (PMID 41301530, 2025). "In addition, we identified a number of genes altered in PTE+ astrocytes that are known to be involved in differentiation, migration, and cell morphology, of which several are associated with epilepsy (i.e., Eml1, Map2, Map1b, Sema3f, and Ptn)." (PMID 37174647, 2023). "In both human and experimental models of epilepsy, decreases in cortical and hippocampal MAP2 immunoreactivity, along with MAP2 dephosphorylation, have been reported." (PMID 28658291, 2017). "In the epilepsy rat model, double-label immunofluorescence staining showed that Npas4 and MAP2 were co-expressed in neurons in the cortex and hippocampus but were not co-expressed with GFAP, an astrocyte marker, in neuroglia cells in the hippocampus and cortex." (PMID 25536221, 2014). "Furthermore, BAO could regulate the expression of GABA, NMDAR1, Notch1, and MAP2 to improve the symptoms of epilepsy." (PMID 35445130, 2022).
melanoma (13 papers, 2010 to 2024). A malignant, usually aggressive tumor composed of atypical, neoplastic melanocytes. "A predicted target of hsa-miR-200c-3p is the microtubule-associated protein MAP2, which seems to act as an inhibitor of melanoma cell proliferation, invasion, and tumor growth." (PMID 37387784, 2023). "Overexpression of MAP2 in melanoma cell lines leads to microtubule stabilization, associated with G2–M phase cell cycle arrest, growth inhibition, and cancer cell apoptosis, both in vitro and in a nude mouse model." (PMID 32823874, 2020). "In this respect, the DNA hypomethylating drug 5-aza-(2-deoxy-)cytidine (decitabine) induced the neuronal marker gene microtubule associated protein 2 (MAP2), progressively methylated during melanoma progression, in metastatic melanoma cells." (PMID 29794999, 2018). "MAP2 expression can be activated in metastatic melanoma cells by treatment with decitabine, which causes promoter demethylation or down-regulation of transcription repressor HES1." (PMID 29179510, 2017). "Microtubule-associated protein 2 (MAP2) has been shown to be a prognostic marker for melanoma patients, and splice variants of MAPT gene demonstrated opposite changes in normal versus prostate tumor." (PMID 21501490, 2011). "Microtubule associated protein 2 (MAP2) is more frequently and abundantly expressed in melanocytic nevi and early primary melanoma than in the metastatic melanoma lesion." (PMID 22545195, 2010). "In both vitro and in vivo, studies have demonstrated that MAP2 expression can reduce melanoma cell growth and proliferation." (PMID 39867879, 2024). "In detail, MAP2 resulted in significantly higher expression in the normal skin tissue when compared to melanoma." (PMID 37387784, 2023). "According to our results, higher hsa-miR-200c-3p levels in melanoma vs. controls and in higher stage melanoma support for a repression of MAP2 expression." (PMID 37387784, 2023). "MAP2 is mainly involved in dendritic morphology and has already been reported as a good prognostic marker in melanoma." (PMID 37387784, 2023). "The expression of MAP2, which is negatively regulated by Notch signaling, was shown previously by our laboratory, in a small cohort of primary melanomas, to predict a better outcome for primary melanoma patients." (PMID 36672468, 2023). "Contrastingly, in malignant melanoma, MAP2 was rarely expressed in metastasis tumors compared with its expression in primary melanoma." (PMID 36188577, 2022). "These genes included SKP2, TOP2A, SOX4, MAP2 and CTLA4, all of which have been associated with patient outcome in melanoma." (PMID 29193607, 2018). "MAP2 promoter activity levels in melanoma cell lines have also been found to correlate with activating mutations in BRAF." (PMID 29179510, 2017). "By blocking BRAF production in metastatic melanoma cells and by forcing MAP2 to be expressed via demethylation by decitabine, we can induce apoptosis." (PMID 29179510, 2017). "It has been reported that in metastatic melanoma cell lines MAP2 expression induces microtubule stabilization, cell cycle arrest in G2-M phase and growth inhibition." (PMID 25415340, 2014). "Studies on regulation of MAP2 promoter in melanoma showed that MAP2 is regulated by Notch1 signaling and by neuronal repressor HES1 and activator NeuroD." (PMID 22545195, 2010). "Ectopic expression of MAP2 in metastatic melanoma cells lines leads to microtubule stabilization, cell cycle arrest in G2-M phase and growth inhibition of metastatic melanoma cells in vitro." (PMID 22545195, 2010). "In this study, we found that treatment of melanoma cells with BCI, a DUSP1/DUSP6 inhibitor at a concentration close to IC50 for selective inhibition of DUSP1, caused upregulation of nestin and immature MAP2 in MAPKi-sensitive cells." (PMID 35999349, 2022). "Induction of MAP2 in melanoma can be exploited as strategy for melanoma prevention and therapy." (PMID 22545195, 2010).
melanoma (continued). "MAP2 was proposed as a diagnostic marker in pulmonary neuroendocrine carcinomas, some non-small-cell lung carcinomas, Merkel cell carcinomas, and oral squamous cell carcinoma, but not in metastatic melanomas (while abundant in primary melanomas)." (PMID 32823874, 2020). "MAP2 expression in melanoma may also be related to the activation levels of BRAF-MEK signaling." (PMID 22545195, 2010). "Using primary tumors from a larger cohort, we showed that MAP2 expression did not significantly predict a longer disease-free survival for primary melanoma patients." (PMID 36672468, 2023). "Because BRAF oncogene levels appear to regulate melanoma neuronal differentiation and tumor progression, blockade of BRAF production with vemurafenib and forced MAP2 expression by demethylation with decitabine could induce apoptosis in metastatic melanoma." (PMID 29179510, 2017). "MAP2 is expressed abundantly in early invasive primary melanoma lesions, but not found in metastatic melanoma lesion and cell lines." (PMID 22545195, 2010).
depression (12 papers, 2013 to 2023). "We have recently found that the synthetic neurosteroid derivative 3β-methoxypregnenolone, which binds to the microtubule-associated protein-2, can provide a novel therapeutic approach in experimental model of depressive disorders in rats." (PMID 26476437, 2016). "Consistently with these changes in MAP2, MT dynamics was also found affected in animal models of depression as reflected by altered expression of α‐tubulin PTMs such as the Tyr/Glu‐Tub ratio and Acet‐Tub in the hippocampus." (PMID 34495563, 2022). "MAP2-IR reduction has additionally been reported in the DLPFC of individuals with major depressive disorder and in the hippocampus of major depression and bipolar disorder subjects." (PMID 36187353, 2022). "Regarding α‐tubulin PTMs, it is still not clear how treatment with PME prevents their reported alterations in animals models of depression; however, a positive correlation between the MT‐binding of MAP2 and the increase of Acet‐Tub has already been demonstrated." (PMID 34495563, 2022). "PREG and PME promote microtubule dynamics by possibly affecting the microtubule‐binding of MAP2 and the plus‐end tracking protein CLIP170 with possible therapeutic potential for major depressive disorders and CDKL5 deficiency disorder, both characterised by altered microtubule dynamics." (PMID 34495563, 2022). "In this study, we found that behavioral symptoms of depression on mice models with the decrease of BrdU/NeuN- and Dcx-positive populations and MAP-2 expression in hippocampus were induced by cranial irradiation, and transthyretin (TTR) was highly expressed in hippocampus after irradiation." (PMID 29849106, 2018). "PBM via NIR irradiation alleviated anxiety and depression symptoms, as well as neuronal cell death, in TgF344-AD mice, and it suppressed neuronal degeneration by increasing the expression of MBP, MAP2, and PSD95, which are nerve fiber and synapse markers." (PMID 37895108, 2023). "The dendritic spine densities and neuron numbers and the protein levels of MAP-2, PSD-95, and SYN were decreased in the hippocampi of rats with CUMS-induced depression, and these trends were reversed by EA." (PMID 34777532, 2021). "While serum from all patients increased the number of DCX+ cells and neuronal (MAP2+) cells between TW0 and TW4, patients who developed IFN-α–induced depression had a significantly lower increase in the number of DCX+ cells between TW0 and TW4." (PMID 31207337, 2019). "Secondly, we assessed whether changes in neurogenic (DCX and MAP2) and apoptotic markers (CC3) detected upon treatment with TW4 serum samples were able to predict later depression." (PMID 31207337, 2019). "In contrast, microarray data indicates no change in MAP2 mRNA expression in depression." (PMID 36187353, 2022). "As the current study demonstrated that decreases in MAP2, a protein expressed in dendrites, was observed within the CA1 and CA3 sub-regions of the hippocampus, this aligns with previous psychiatric studies showing the significant role the pathophysiology of the hippocampus plays in depression." (PMID 34955781, 2021). "However, there was no significant change in MAP2 levels in the rats with anxiety-like phenotype and rats with depression-like phenotype as compared with the controls." (PMID 30740068, 2018). "Here, we used them to study the roles of RACK1/NR2B, AKAP/PKA and MAP2/PKA complexes in the RSC and establish whether mechanisms mediating remote fear extinction from other anxiety- and depression-related behaviors can be differentiated at the level of discrete NR2B and PKA signaling." (PMID 26460481, 2015). "Therefore, we hypothesize that MAP2 and tau would also show differential expression in the hippocampal formation of MTLE patients with major depression and interictal psychosis." (PMID 24069608, 2013).
depression (continued). "Interestingly, an increase in peripheral levels of MAP2 in bipolar depression has recently been reported as well, while one post-mortem study also showed an increase in pyramidal neuronal density in the CA1 in chronic MDD." (PMID 35794184, 2022). "Two MAP2 phosphorylation events in the projection domain (pS233 and pS1031) have been reported to be decreased (case:control ratio = 0.82–0.83) in DLPFC of individuals with major depression, though these changes did not remain significant after controlling for false discovery rate." (PMID 36187353, 2022).